ENSG00000272442 (novel protein, TMEM151B-SPATS1 readtrough)
Gene: Protein-coding gene on chromosome 6 (44,273,194 to 44,378,957, forward strand). Ensembl gene ENSG00000272442.
Genetic constraint (gnomAD): Missense variants: 134 observed, 201.3 expected, observed/expected ratio (o/e) 0.67, 90% interval 0.58 to 0.77. Synonymous variants: 65 observed, 74.38 expected, observed/expected ratio (o/e) 0.87, 90% interval 0.71 to 1.07.